INS (insulin)
Diseases named in the same sentence as INS in open-access papers (continued):
Sharing a sentence is not in itself a finding about the gene and the disease.
diabetes (continued). "Diabetes mellitus is a chronic metabolic disorder that is characterized by elevated blood glucose caused by deficiency or resistance to insulin." (PMID 30775002, 2019). "Subsequently, HbA1c increased to 11.4% (101 mmol/l) at the age of 12 years when an oral glucose tolerance test suggested insulin deficient-diabetes mellitus." (PMID 29739729, 2019). "Women with diabetes treated with insulin were also found to have significantly higher risk for LGA children (p = 0.002)." (PMID 31064335, 2019). "In type 2 diabetes mellitus, defective insulin secretion is caused by beta cell dysfunction, and the number of the beta cell was reduced." (PMID 31212585, 2019). "Diabetes mellitus is a metabolic disorder characterized by the presence of high levels of glucose in blood that occurs either due to insulin's deficiency or malfunction." (PMID 31708869, 2019). "The 14 bp INS/DEL polymorphism in the 3′UTR of HLA-G can also have an effect on the susceptibility to diabetes and coronary artery diseases (CHD), therefore suggesting a novel candidate gene." (PMID 31663031, 2019). "The effect of insulin on cardiovascular risk is difficult to analyse, as insulin use is confounded by poor glycaemic control, more advanced diabetes and subsequent increased risk of cardiovascular events." (PMID 31766545, 2019). "The proliferation of pancreatic β cells is regulated by cell cycle progression, and a decrease in β cell proliferation is the main cause of diabetes where insulin secretion is insufficient." (PMID 30736847, 2019). "Diabetes mellitus (DM) is a group of metabolic disorders characterised by uncontrollable high blood glucose levels caused by defects in insulin action, insulin secretion, or both." (PMID 30719343, 2019). "The findings of the present study suggested that human insulin use in patients with type 2 diabetes mellitus was associated with an increased risk of lung cancer in a dose-response pattern." (PMID 31354621, 2019). "In the present study, we investigated the insulin secretory effects of A. annulatum and its bioactive compounds and the underlying mechanisms to find a favorable alternative therapy for diabetes." (PMID 31382473, 2019). "Diabetes mellitus (DM), characterized by chronic hyperglycemia caused by deficiency in insulin secretion or resistance against insulin, is the most prevalent metabolic disorder worldwide, and it currently affects over 350 million people globally." (PMID 30988065, 2019). "Diabetes mellitus is a chronic disease due to the deficiency or ineffective of the pancreas to produce insulin." (PMID 31075966, 2019). "Pancreatic β-cell apoptosis contributes to the loss of insulin-producing β-cells in diabetes, rapidly induced by the activation of the immune system in T1D and slowly progressing in T2D1–4,6–11." (PMID 31676778, 2019). "While diabetes has long been linked to impaired insulin secretion, recently, glucagon has received much attention with respect to its role in diabetes." (PMID 31829209, 2019). "The concept of β-cell dedifferentiation, marked by loss of β-cell insulin expression and increased expression of Ngn3 (a marker of islet progenitor cells), has been corroborated in animal models of diabetes." (PMID 31440379, 2019). "In each islet around 50 beta-cells were analyzed, with exception of the rats with overt diabetes, in which a concomitant loss of insulin-positive beta-cells was observed." (PMID 30631045, 2019). "Change in waist circumference was also significantly correlated with most diabetes risk markers, including fasting glucose and fasting insulin." (PMID 31002638, 2019). "Type 2 diabetes mellitus (T2DM) is a common metabolic syndrome caused by the inability of pancreatic β cells to produce enough insulin or the body’s inability to use insulin effectively." (PMID 31717456, 2019). "STZ-induced diabetes is caused by the selective destruction of insulin-secreting pancreatic β-cells; therefore, STZ is the first choice for diabetes induction in animal models." (PMID 31197747, 2019).
diabetes (continued). "Voltage-gated Ca2+ (CaV) channels trigger glucose-induced insulin secretion in pancreatic beta-cell and their dysfunction increases diabetes risk." (PMID 30911681, 2019). "A positive association was also found for the presence of diabetes and two medications as insulin and diuretic use." (PMID 31142774, 2019). "According to an earlier study, childhood obesity, intra uterine growth retardation, parental obesity and diabetes were associated with PT, we therefore also assessed insulin resistance parameters in the participants." (PMID 31856872, 2019). "Type 2 diabetes (T2D) is the most common form of diabetes constituting about 90% of the diabetic population, characterized by elevated levels of plasma glucose which is caused by impairment in both insulin secretion and its action." (PMID 31341469, 2019). "Patients that carry a partial loss-of-function variant of AKT2 tend to have a higher level of fasting plasma insulin and an increased risk of developing diabetes mellitus." (PMID 31835296, 2019). "In children with type 1 diabetes mellitus, serum irisin concentrations are positively associated with bone quality and with glycemic control following continuous subcutaneous insulin infusion." (PMID 31091695, 2019). "The results showed that the diabetes patient had a stronger association with depressive symptoms if they used both oral agents and insulin injection." (PMID 31726788, 2019). "The Diabetes Control and Complications Trial showed that close to diagnosis preserved endogenous insulin was associated with lower HbA1c, hypoglycaemia and complication rates, when intensively treated." (PMID 30955221, 2019). "High levels of blood urea nitrogen (BUN) increased risk of insulin use, and serum creatinine (Scr) concentration is inversely related to the incident of diabetes." (PMID 31805910, 2019). "On the other hand, PDAC itself is known to cause diabetes mellitus by reducing insulin release, enhancing insulin resistance, and leading to new onset diabetes mellitus, which is diagnosed in more than 60% of patients with this tumor type." (PMID 30764482, 2019). "At the same time, diabetes empowerment was associated with executive functions, disease duration, metabolic control, and insulin doses." (PMID 31183368, 2019). "During IR, the body’s compensatory release of excess insulin to maintain blood sugar stability causes hyperinsulinemia that can progress to type 2 diabetes mellitus (T2D)." (PMID 31258478, 2019). "Studies in the rat STZ model of T1DM have demonstrated that treatment with insulin can largely reverse diabetes-associated bladder hypertrophy within a few weeks." (PMID 31474866, 2019). "Several possible mechanisms have been proposed to mediate the protective role of vitamin D against diabetes risk including alterations in the pancreatic β-cell function, insulin sensitivity and systemic inflammation." (PMID 32153959, 2019). "Data on sociodemographic and clinical characteristics including duration of diabetes, type of insulin they have been taking, the factors associated with hypoglycemia, and the severity stage of hypoglycemia was obtained." (PMID 31093506, 2019). "Pre-clinical studies have noted that NADPH oxidase 2 deficient mouse models carrying non-functional allele of either Cybb (gp91phox) or Ncf1 are resistant to diabetes development and exhibit enhanced insulin secretion in response to glucose." (PMID 31118934, 2019). "Diabetes mellitus (DM) is the most common progressive disease which is characterized as continuous hyperglycemia due to the impairment of insulin production by pancreatic β-cells and/or caused by peripheral insulin resistance." (PMID 30959759, 2019). "Only two studies have assessed built environment and cancer risk factors such as insulin and diabetes, with findings indicating that PA supportive environments are associated with better insulin and diabetes outcomes." (PMID 30760246, 2019).
diabetes (continued). "Despite consistent findings among adults, data on the effects of dietary fiber consumption in younger populations at risk of diabetes or reduction in glycemia and/or the insulin response are quite limited." (PMID 31684015, 2019). "An analog carrying this mutation, insulin X10, was developed as a rapid-acting drug lead for diabetes but was ultimately halted due to its mitogenic properties." (PMID 30747102, 2019). "Diabetes mellitus (DM) is a metabolic disease characterized by an increase in chronic blood glucose levels due to defects in insulin secretion and action, causing multisystem damage." (PMID 31073305, 2019). "The most likely reason is that defects in β-cell function are more severe in Chinese patients with diabetes than those in Europeans or Americans, resulting in more serious deficiencies in insulin secretion." (PMID 31690291, 2019). "This is often difficult due to the death/loss of function of the insulin-producing beta cells in the pancreas which accompanies diabetes." (PMID 31781665, 2019). "Physical activity has beneficial effects on obesity, diabetes, lipid profile, endothelial function and insulin sensitivity, and inflammation, which are all important risk factors of CV events." (PMID 31146702, 2019). "We found that the biological functions of the DIA-DB diabetes drug targets to be associated with glucose and lipid homeostasis as well as insulin secretion and sensitivity and that some of these targets were interconnected." (PMID 31703341, 2019). "Whereas lack of insulin synthesis and/or secretion defines type 1 diabetes, tissue resistance to the action of insulin constitutes the hallmark of type 2 diabetes, which represents more than 90% of the cases of diabetes." (PMID 31212580, 2019). "Insulin analogs are considered as effective as human insulins on the treatment of diabetes; however, with a smaller risk of causing hypoglycemia." (PMID 30786308, 2019). "EDs and DEB have been thought to be associated in various ways with diabetes mellitus (DM), a group of metabolic diseases characterized by chronic hyperglycemia resulting from defects in insulin secretion, insulin action, or both." (PMID 31695914, 2019). "Diabetes mellitus is a metabolic disease secondary to either the deficiency or decreased responsiveness of tissues to insulin and is associated with derangements in the metabolism of carbohydrates, lipids, and proteins." (PMID 31687307, 2019). "The treatment of diabetes-related complications, such as cardiovascular disease, retinopathy and neuropathy, makes up the largest part of the direct medical costs associated with diabetes care, with less than 10% spent on insulin and anti-diabetic drugs." (PMID 31796048, 2019). "In our current investigations for the protection of β cells against glucotoxicity, we used STZ-treated mice as a type 1-like insulin-deficient diabetes model." (PMID 31467926, 2019). "Insulin resistance, or reduced responsiveness of body tissues to insulin, is the hallmark of type 2 diabetes mellitus (T2DM)." (PMID 31976335, 2019). "The markedly decreased level of insulin observed in the diabetic animals ultimately leads to the impairment in the activity of hexokinase, since insulin deficiency is a clinical imprint of diabetes." (PMID 31142215, 2019). "Decreases in insulin secretion, obesity, and vitamin D deficiency were known to contribute for developing diabetes in elderly population." (PMID 31641666, 2019). "Diabetes mellitus (DM) is a metabolic disorder, where insulin resistance or the reduced levels of secreted insulin cause hyperglycemia." (PMID 31191707, 2019). "Diabetes mellitus is a chronic disease caused by inherited and/or acquired deficiency in insulin production by the pancreas or by the ineffectiveness of the insulin produced." (PMID 31266160, 2019).
diabetes (continued). "It has been reported that this polymorphism also determines glucose-stimulated insulin secretion and plasma glucose concentrations and thus increases the type 2 diabetes mellitus (T2DM) risk in European populations." (PMID 30926842, 2019). "Anti-diabetes medications, including sulfonylureas, meglitinides, and insulin, are associated with hypoglycemia and their doses should be adjusted on days of intermittent fasting." (PMID 31003482, 2019). "Type 2 diabetes mellitus is caused by environmental resistance to insulin action, impaired insulin secretion, and enhanced glucose production in the liver." (PMID 35919481, 2019). "Strict glucose control using multiple doses of insulin is the standard treatment for type 1 diabetes mellitus (T1DM), but increased risk of hypoglycemia is a frequent drawback." (PMID 30622653, 2019). "Specifically, the response to insulin is associated with each phenotype with corrected p-values of 1E-9, 0.04 and 0.005, respectively for Diabetes, Obesity and Ovarian Cyst." (PMID 31307376, 2019). "Uninhibited actions of lipolytic hormones on fat cells due to impairment of insulin secretions result in hypertriglyceridemia and hypercholesteromia in diabetes that further increase the risk of cardiovascular diseases." (PMID 31186667, 2019). "In humans, primary aldosteronism (PA), a leading cause of secondary hypertension, has been associated with diabetes due to impaired insulin sensitivity and/or insulin secretion." (PMID 31091693, 2019). "With the chronic overconsumption of calories causing the overstimulation of insulin and the increased rate of lipogenesis, it is easy to predict the rise of diabetes and obesity in the same patient populations." (PMID 31244777, 2019). "Despite the multiple well-known benefits of adherence to insulin therapy, poor adherence remains to be a common cause of diabetes mellitus-related complications." (PMID 31692777, 2019). "The reduced insulin level in the cerebrospinal fluid was observed in rats with type 2 diabetes mellitus associated with obesity and hyperinsulinaemia." (PMID 30870482, 2019). "Diabetes mellitus, a global epidemic disease, is the most common metabolic disorder caused by the impairment of insulin secretion and glucose metabolism." (PMID 31083617, 2019). "The failure of pancreatic insulin-producing β-cells is a central pathogenic hallmark of all forms of diabetes." (PMID 31815004, 2019). "Mice with a disruption to BMAL1 exhibit impaired glucose tolerance and decreased insulin secretion, resulting in hyperglycemia and a higher risk for type 2 diabetes mellitus compared with wild-type mice." (PMID 31216190, 2019). "Enhanced intima hyperplasia in diabetes is mainly due to insulin signaling via homo-IR, associated with increased Has2 expression." (PMID 31562314, 2019). "When using complex insulin regimen in old people with diabetes, attention should be paid for the risk of hypoglycemia." (PMID 30833929, 2019). "The underlying mechanisms by which a mutation causes HH and diabetes later in life have been suggested as pancreatic beta-cell apoptosis due to overstimulation of insulin secretion, enhanced cell depolarization, and increased intracellular calcium influx." (PMID 31137773, 2019). "Individuals with diabetes who were also taking insulin were more likely to suffer from an IS than their counterparts (HR=2.58; 95% CI=1.61 to 4.15), indicating that insulin use significantly increased diabetic individuals’ risk of suffering from an IS." (PMID 31127075, 2019). "Intermittent fasting, when undertaken for health reasons in patients with diabetes mellitus, both types 1 and 2, has been shown in a few small human studies to induce weight loss and reduce insulin requirements." (PMID 31003482, 2019).
diabetes (continued). "Twenty-one per cent (123/583) of insulin-treated participants diagnosed with diabetes after 30 years of age met the study criteria for type 1 diabetes and had severe endogenous insulin deficiency (insulin treatment within 3 years and C-peptide <200 pmol/l)." (PMID 30969375, 2019). "Type 1 diabetes mellitus (T1DM) is characterized by a deficiency in insulin secretion from β-cells, resulting in hyperglycemia and impaired glucose metabolism." (PMID 31083617, 2019). "In our study, the presence of diabetes and the use of insulin were positively associated with IMT-CC; though fasting insulin did not." (PMID 31142774, 2019). "The liver is another organ that highlights the most recent basic and clinical data underlying the development of diabetes where fatty liver and diabetes share insulin resistance as their pathogenic determinant." (PMID 30917540, 2019). "Diabetes is a disease, caused by abnormal metabolism of carbohydrates due to defects in insulin secretion, caused by pancreatic dysfunction or deficiency of insulin receptors on the cell surfaces." (PMID 32184874, 2019). "The presence of GADA and ZnT8A in our cohort hardly indicate the increased risk for type 1 diabetes as only one patient developed insulin treated diabetes during follow-up." (PMID 30783963, 2019). "It has been demonstrated that insulin resistance in ECs causes skeletal muscle insulin resistance due to reduced insulin-induced capillary recruitment and insulin delivery, leading to diabetes." (PMID 31013778, 2019). "Diabetes mellitus (DM) is a metabolic disorder characterized mainly by the presence of chronic hyperglycemia due to a deficiency of insulin secretion or insulin resistance." (PMID 31731539, 2019). "Misdiagnosis of monogenic diabetes as Type 1 diabetes can result in unnecessary insulin treatment, causing suboptimal glucose control, higher management costs and avoidable side effects." (PMID 31276222, 2019). "Type 2 diabetes mellitus (T2DM) is a chronic metabolic disease associated with higher blood glucose levels as a result of insufficient insulin secretion, insulin action or both." (PMID 30674322, 2019). "Diabetes mellitus (DM) is a chronic metabolic disorder characterized by high level of glucose in the blood resulting from a relative or absolute deficiency of insulin action." (PMID 31178917, 2019). "Diabetes mellitus (DM) is a metabolic syndrome characterized by hyperglycemia that occurs as a result of deficient insulin secretion and/or action." (PMID 30915195, 2019). "Islet β‐cell membrane excitability is a well‐established regulator of mammalian insulin secretion, and defects in β‐cell excitability are linked to multiple forms of diabetes." (PMID 31161721, 2019). "An increased rate of change in unmethylated INS ratio from baseline to diabetes onset (a slope that was 10 times steeper) was associated with a five-year decrease in age at T1D diagnosis." (PMID 31398795, 2019). "Diabetes is a global health problem caused primarily by the inability of pancreatic β-cells to secrete adequate levels of insulin." (PMID 31171772, 2019). "Diabetes is now recognised as a chronic metabolic disease caused by relative insulin deficiency, reduced insulin sensitivity of body tissues, or a combination thereof." (PMID 31516543, 2019). "βICKO mice manifest impaired insulin secretion in combination with a loss of β-cell mass similar to that reported for Type 2 Diabetes mellitus patients." (PMID 31831727, 2019). "For example, plasma levels of fasting glucose are associated with insulin sensitivity and diabetes or plasma cholesterol and triglycerides are linked to cardiovascular disease." (PMID 31100942, 2019). "Insulin resistance directly disturbs the physiological regulation of insulin in target organs, resulting in hyperlipidemia and hyperglycemia associated with diabetes, which in turn, feeds back on pancreatic islets and reduces insulin secretion." (PMID 30945455, 2019).